SPARCL1 (SPARC like 1)
Diseases named in the same sentence as SPARCL1 in open-access papers (continued):
Sharing a sentence is not in itself a finding about the gene and the disease.
ovarian carcinoma (7 papers, 2007 to 2026). A malignant neoplasm originating from the surface ovarian epithelium. "One study showed that SPARCL1 was involved in the regulation of drug resistance in ovarian cancer by comprehensive bioinformatic analysis." (PMID 35111844, 2022). "A previous report similarly showed SPARCL1 suppresses the proliferation and migration of human ovarian cancer." (PMID 30987093, 2019). "While DOCK4 regulates formation of cellular junctions and is disrupted in prostate and ovarian cancers,SPARCL1 acts as a negative regulator of cell proliferation and its down-regulation is detected in prostate, colon, and non-small cell lung carcinomas." (PMID 17559657, 2007). "SPARCL1 bound to miR-539-3p to regulate ovarian cancer cell proliferation and metastasis." (PMID 35549806, 2022). "Moreover, miR-539-3p was found to promote cell invasion by targeting SPARCL1 in epithelial ovarian cancer." (PMID 33980221, 2021). "For example, SPARCL1 inhibited cell proliferation and invasion by inhibiting the mitogen-activated protein kinase kinase (MEK) and extracellular signal-related kinase (ERK) pathways in ovarian cancer." (PMID 33980221, 2021).
Alzheimer disease (5 papers, 2020 to 2025). A progressive, neurodegenerative disease characterized by loss of function and death of nerve cells in several areas of the brain leading to loss of cognitive function such as memory and language. "Of note, SPARCL1 has been recently identified as part of a network of genes linked to neuronal damage in the preclinical stages of Alzheimer’s disease (AD)." (PMID 32993090, 2020). "SPARCL1 has been investigated in Alzheimer’s disease and multiple sclerosis, where its roles in neuroinflammation, astrocytic activation, and synaptic remodeling have been highlighted in experimental studies." (PMID 41009953, 2025). "Some of these genes have already been linked to serious neurological conditions, such as SCN7A, which has been associated with amyotrophic lateral sclerosis, GLIS1 with Parkinson’s Disease and SPARCL1 with neuroinflammation in Alzheimer’s Disease." (PMID 36980268, 2023). "We are also interested in the effect of Sparcl1 fusion on known aggregation-prone proteins in the field of neurodegenerative diseases, such as amyloid β in Alzheimer’s disease, α-synuclein in Parkinson’s disease, huntingtin protein in Huntington’s disease, and SOD1 in amyotrophic lateral sclerosis." (PMID 38474544, 2024).
glioblastoma (4 papers, 2022 to 2026). The most malignant astrocytic tumor (WHO grade IV). "SPARCL1 overexpression in experimental glioblastoma resulted in increased microvascular density and angiogenesis." (PMID 37509139, 2023). "SPARCL1 expression significantly enhanced the microvascular proliferation and tumor neo-angiogenesis of glioblastoma." (PMID 37509139, 2023). "For example, the enhanced SPARCL1 expression contributed to tumor infiltration and angiogenesis of glioblastoma, further improving preclinical modeling of glioblastoma." (PMID 35549806, 2022). "Publicly available transcriptomic datasets from the Ivy Glioblastoma Atlas Project (Ivy GAP), GlioVis, and TCGA were analyzed to evaluate SPARCL1 expression across GBM cohorts." (PMID 42123596, 2026). "Likewise, IGF-1, IGFBP2, SPARCL1, kininogen-1, osteopontin, and GRP78 are known to be secreted by glioblastoma cells." (PMID 35659255, 2022).
lung adenocarcinoma (4 papers, 2017 to 2024). A carcinoma that arises from the lung and is characterized by the presence of malignant glandular epithelial cells. "Nevertheless, some studies demonstrated that SPARCL1 expression had less influence on some lung adenocarcinoma cohorts (GSE 31210 and GSE 13213)." (PMID 36483097, 2022). "Gene expression analysis revealed that four of the five genes, HOXA9, TAL1, ATP8A2, ENG and SPARCL1, each harboring one of the five frequently hypermethylated CpG sites within its promoters, were also frequently down-regulated in lung adenocarcinoma." (PMID 28178989, 2017). "Accordingly, we found five genes (HOXA9, TAL1, ATP8A2, ENG and SPARCL1) corresponding to the five CpG sites had above 90% hypermethylation frequencies in the 539 lung adenocarcinoma samples from TCGA." (PMID 28178989, 2017). "Especially, we found three genes (SPARCL1, ENG and TAL1) harboring frequently hypermethylated CpG sites within their promoters were also frequently down-regulated in lung adenocarcinoma." (PMID 28178989, 2017). "Thus, SPARCL1 and TAL1 might also be important tumor suppressors of lung adenocarcinoma and it would be interesting to study whether their silencing could be reactivated by demethylation and whether the reactivation could suppress cancer cells." (PMID 28178989, 2017).
Obesity (4 papers, 2021 to 2025). Accumulation of substantial excess body fat. "This family includes molecules, such as SPARC, SPARCL-like 1 (SPARCL1), thrombospondin 1 and 2, and osteopontin, all of which have been implicated in the development of obesity, insulin resistance, and chronic liver diseases." (PMID 40243151, 2025). "On the other hand, SPARCL1 may provide new therapeutic targets for metabolic diseases caused by obesity, which can help us better understand adipose differentiation and metabolism." (PMID 34872433, 2021). "Thus, AT SPARCL1 could be targeted to treat obesity-associated NASH." (PMID 35909571, 2022). "We also analyzed the expression of FBXW7, MBOAT2, STXBP4, SPARCL1, and UTS after SLFN12 overexpression because these are obesity-related genes." (PMID 36291149, 2022). "They identified SPARCL1 as a new protein factor preferentially secreted from epididymal SVF and found that it can inhibit adipocyte differentiation and may contribute to increased adipocyte hypertrophy in obesity." (PMID 35909571, 2022).
pulmonary hypertension (4 papers, 2022 to 2025). Increased pressure within the pulmonary circulation due to lung or heart disorder. "Sparc contributes to angiogenesis, with both pro-angiogenic and anti-angiogenic effect reported, while Sparcl1 has recently been reported as a biomarker of maladaptive right ventricular remodelling in pulmonary hypertension." (PMID 34528097, 2022). "In addition, increased plasma levels of SPARCL1 have been found in patients with maladaptive right ventricular function from pulmonary hypertension." (PMID 34929167, 2022). "Emerging biomarkers for RV maladaptation in pulmonary hypertension are long non-coding RNA H19, SPARC-like protein 1 (SPARCL1), and cartilage intermediate layer protein 1 (CILP1)." (PMID 39064541, 2024).
rectum adenocarcinoma (4 papers, 2021 to 2024). An adenocarcinoma arising from the rectum. "Especially, marker sets of M2 macrophages were strongly related to SPARCL1 in cholangiocarcinoma, colon adenocarcinoma, rectum adenocarcinoma, and pancreatic adenocarcinoma." (PMID 36483097, 2022). "SPARCL1 was correlated with stromal score, immune score, and ESTIMATE score in both colon adenocarcinoma (COAD) and rectum adenocarcinoma (READ)." (PMID 35111844, 2022).
renal cell carcinoma (4 papers, 2020 to 2025). "In another study, we found the inhibitory role of SPARCL1 in renal cell carcinoma cell metastasis, which might be due to the inactivation of p38/JNK/ERK MAPKs." (PMID 35549806, 2022). "SPARCL1 (secreted protein acidic and cysteine-rich like 1), a member of the SPARC family, may act as a tumor suppressor in renal cell carcinoma, regulating disease progression through the p38/JNK/ERK pathway." (PMID 41300790, 2025). "Through the mouse kidney injury model experiment, SPARCL1 showed that mRNA expression was not changed in the acute phase, but the expression level was high in the fibrosis of the kidney, and it inhibited the movement and invasion of renal cell carcinoma." (PMID 32545899, 2020).
autism (3 papers, 2022 to 2024). Persistent deficits in social interaction and communication and interaction as well as a markedly restricted repertoire of activity and interest as well as repetitive patterns of behavior. "Downregulation or missense mutations in SPARCL1/Hevin have been reported in numerous neurological disorders such as autism, schizophrenia, and depression." (PMID 37291094, 2023). "Regulatory inference using the Genie3 algorithm identified direct regulation of IGF1 by SIK1, MFRP, CHD7, NIPBL, EXOC5, and ARID2, with SIK1 and SPARCL1 significantly downregulated in autism brain organoids, potentially affecting IGF1 expression." (PMID 39376742, 2024).
autism spectrum disorder (3 papers, 2022 to 2025). A spectrum of developmental disorders that includes autism, and Asperger syndrome. "Sparcl1 is expressed in a variety of cell types, including neurons, and genetic mutations in SPARCL1 are associated with multiple sclerosis and autism spectrum disorders." (PMID 38474544, 2024). "Notably, previous studies indicated that SPARCL‐1 mutations are associated with an increased risk of autism spectrum disorder, providing another piece of evidence that its regulation impacts the normal functioning of synapses." (PMID 39935382, 2025). "Mutations in the SPARCL1 gene increase the risk of autism spectrum disorder (ASD)." (PMID 35831437, 2022).
bladder cancer (3 papers, 2011 to 2024). "However, underlying functions of SPARCL1 in bladder cancer (BCa) remain understudied." (PMID 39548034, 2024).
cholangiocarcinoma (3 papers, 2022 to 2024). A carcinoma that arises from the intrahepatic biliary tree (intrahepatic cholangiocarcinoma) or from the junction, or adjacent to the junction, of the right and left hepatic ducts (hilar cholangiocarcinoma). "Conversely, SPARCL1 was found to be upregulated in kidney chromophobe (KICH), kidney renal clear cell carcinoma (KIRC), liver hepatocellular carcinoma (LIHC) (p < 0.001), and cholangiocarcinoma (CHOL) (p < 0.01)." (PMID 39548034, 2024). "The SPARCL1 expression level was elevated in kidney chromophobe (KICH), kidney renal clear cell carcinoma (KIRC), liver hepatocellular carcinoma (LIHC) (p < 0.001), and cholangiocarcinoma (CHOL) (p < 0.01)." (PMID 36483097, 2022).
hepatocellular carcinoma (3 papers, 2022 to 2024). A malignant tumor that arises from hepatocytes. "For instance, SPARCL1 is highly expressed in hepatocellular carcinoma, yet its upregulation restrains cell proliferation in this context." (PMID 39548034, 2024). "Recently, Sparcl1 was reported to be upregulated in liver-specific Apobec1 complementation factor transgenic mice, which is charactered with a phenotype with spontaneous steatosis, fibrosis, and hepatocellular cancer." (PMID 36387870, 2022). "SPARCL1 was mostly undetectable in normal liver tissues but was verified up-regulated in hepatocellular carcinoma (HCC)." (PMID 36483097, 2022).
non-alcoholic steatohepatitis (3 papers, 2021 to 2022). "Sparcl1 was found to be a regulator of nonalcoholic steatohepatitis (NASH) progression." (PMID 36387870, 2022). "As the direction of research has expanded, some reports have shown that the SPARCL1 gene has additional physiological functions, e.g, SPARCL1 inhibits adipogenesis in 3T3-L1 cells; SPARCL1 is highly upregulated in adipose tissue in patients with non-alcoholic steatohepatitis [B. 19, 20]." (PMID 34872433, 2021).
non-small cell lung carcinoma (3 papers, 2006 to 2020). A group of at least three distinct histological types of lung cancer, including non-small cell squamous cell carcinoma, adenocarcinoma, and large cell carcinoma. "Human SPARCL1 expression is also commonly downregulated in other cancer tissues, including CRC, metastatic prostate adenocarcinoma, non-small cell lung cancer, metastases of pancreatic cancer, gastric cancer, breast cancer, and hilar cholangiocarcinoma." (PMID 32437418, 2020).
steatosis (3 papers, 2021 to 2025). Increased lipid within the cytoplasm of cells. "Supporting this, another study reported that SPARCL1 is upregulated in liver-specific Apobec1 complementation factor transgenic mice, a model for steatosis, fibrosis, and hepatocellular carcinoma." (PMID 40243151, 2025). "It revealed that expression levels of HSPD1 mRNA (p = 0.007), MMP14 mRNA (p = 0.015), miR-6881-5p miRNA (p = 0.046) and lncRNA lnc-SPARCL1-1:2 (p = 0.006) were independent predictors of NASH, and NAFLD scoring steatosis grading and fibrosis scoring (p = 0.04)." (PMID 34572434, 2021). "Clinically, plasma SPARCL1 levels are significantly higher in patients with MASH than in normal individuals or patients with simple steatosis, in line with its role in driving steatosis-to-MASH progression." (PMID 40243151, 2025). "We concluded that HSPD1/MMP14/ITGB1/miR-6881-5P/Lnc-SPARCL1-1:2 panel expression has a potential in the diagnosis of NASH, and also in differentiation between NAFLD without steatosis, NAFLD with simple steatosis and NASH." (PMID 34572434, 2021).
brain tumor (2 papers, 2024 to 2025). "Lastly, proteomics analysis revealed that SPRL1 (Sparc like protein 1), the protein encoded by secreted, acidic, and rich in cysteine like 1 (SPARCL1), is highly expressed in mouse brain tumor xenograft models." (PMID 38418476, 2024).
Cirrhosis (2 papers, 2022 to 2023). A chronic disorder of the liver in which liver tissue becomes scarred and is partially replaced by regenerative nodules and fibrotic tissue resulting in loss of liver function. "In this analysis, SPARCL1 was a hub gene in PPI network and Hyper-LG in NAFLD HCC patients with cirrhosis, which reminds us to focus on the role of tumor angiogenesis and metastasis of SPARCL1 in NAFLD of HCC with cirrhosis." (PMID 36397165, 2022). "Another four studies revealed that the serum TGFB2/TGFB2-OT1, lnc-SPARCL1-1:2, lncRNA RABGAP1L-DT-206, MALAT1, Neat1, and HULC expression were significantly higher in patients with advanced fibrosis/cirrhosis (F = 3–4) than in those without it (F = 0–2)." (PMID 36979495, 2023). "Compared to non-NAFLD of HCC patients with cirrhosis, GNG4, EPCAM, SPARCL1, DGKK, and SLC39A4 were down-regulated and HOXD9 was up-regulated in NAFLD of HCC patients with cirrhosis." (PMID 36397165, 2022).
Cognitive impairment (2 papers, 2017 to 2025). Abnormal cognition is characterized by deficits in thinking, reasoning, or remembering. "Moreover, the results of PPI analysis indicated that TBI-induced cognitive impairment is a multifactorial process of pathological progress that involves various proteins that interact with each other including the SPARCL1-CALM-ACTC1-TUBA4A-GAPDH-LPL-SHBG-SERPINA6 network." (PMID 28251161, 2017).
corneal dystrophy (2 papers, 2024). The term corneal dystrophy embraces a heterogeneous group of bilateral genetically determined non-inflammatory corneal diseases that are usually restricted to the cornea. "The variant and gene, SPARCL1, indeed is a possible cause for new corneal dystrophy, but because only one family is presented, we need to wait for new unrelated affected patients with pathogenic variants in the same gene to emerge." (PMID 39394466, 2024). "Therefore, this article is important so that inherited corneal dystrophy researchers can now examine the SPARCL1 gene in their genetically unsolved samples, and the gene can be added to clinical gene panels." (PMID 39394466, 2024).
COVID-19 (2 papers, 2024). A disease caused by infection with severe acute respiratory syndrome coronavirus 2. "In a previous study carried out by Zhao and his collaborators in 2024, it was demonstrated how lung capillary ECs presented altered transcriptomics and adopted a different phenotype after viral injury, such as COVID-19, to generate high levels of SPARCL1." (PMID 39273209, 2024). "Here the authors report that SPARCL1 expressed in pulmonary capillary endothelial cells contributes to immune pathology in mouse model via pro-inflammatory macrophage induction, while circulating SPARCL1 levels corelate with COVID-19 lethality." (PMID 38762489, 2024). "Finally, SPARCL1 expression is increased in lung ECs from COVID-19 patients when compared with healthy donors, while fatal COVID-19 correlates with higher circulating SPARCL1 protein levels in the plasma." (PMID 38762489, 2024). "In fact, circulating SPARCL1 was higher in patients who died from COVID-19, unlike recovered sick patients, where the levels of this protein were much lower." (PMID 39273209, 2024).